FOXM1 (forkhead box M1)
Diseases named in the same sentence as FOXM1 in open-access papers (continued):
Sharing a sentence is not in itself a finding about the gene and the disease.
tumor (continued). "HuR and FOXM1 are both involved in enhancing HGSOC cell viability and promoting tumor growth." (PMID 35624501, 2022). "Yuan at al. confirmed that ASPM, FOXM1, RACGAP1, and TPX2 were significantly associated with not only tumor progression but also prognosis of ACC." (PMID 35693556, 2022). "Furthermore, by performing IHC staining using mouse tumor tissues, we found that SR9009 treatment reduced the expression of FOXM1 and its target genes CCNB1, CCNB2 and Survivin." (PMID 36357378, 2022). "The public database revealed a significant correlation between expression of DKK1 and FOXM1 mRNAs in the tumor lesions of PDAC and ESCC but not in EAC." (PMID 34117362, 2021). "Data in the Cancer Genome Atlas (TCGA) project showed that FOXM1 is generally overexpressed in tumor tissues but not in normal tissues." (PMID 34880209, 2021). "The tumor markers CDKN2A and KRT7 were the most upregulated genes with fold changes 10.7 and 4.8, respectively, while markers for proliferation (MELK, CDK1, MKI67, CCNB2, BUB1, FOXM1, CDKN3) had fold changes spanning from 2.0–2.7." (PMID 35008799, 2021). "Previous studies reported that FOXM1, ERG, and MYBL2 played a role in tumor immune infiltration." (PMID 34489925, 2021). "In addition, we show that this mechanism is partly disrupted in anoikis/antimitotics-resistant tumor cells, with resistance correlating with lower BMF expression but in a FOXM1-independent manner." (PMID 34035233, 2021). "In addition, we found repressed ERBB2 (HER2) and FOXM1 signaling by IPA, both of which are involved in tumor progression and metastasis." (PMID 33743824, 2021). "Our work, thus, strongly advocates that FoxM1 overexpression offers HCC cells a remarkable growth advantage and its targeted knockdown successfully sensitized conventionally resistant tumor cells to therapeutic regimes, including Artemisinin." (PMID 34900697, 2021). "The correlation between the ratios of tumor lesions with positive DKK1 and FOXM1 staining was confirmed, namely tumor lesions which highly expressed DKK1 were also positive for FOXM1, and tumor lesions not expressing DKK1 were negative for FOXM1." (PMID 34117362, 2021). "Overall, these observations indicated that LECT2 might antagonize FOXM1 signaling via targeting HGF/MET, which affects multiple biological processes and slow down PDAC tumor formation and metastasis." (PMID 33937262, 2021). "Thus, this analysis supports that tumor cells with lower BMF expression are more resistant to anoikis-inducing drugs, and independently of FOXM1 expression." (PMID 34035233, 2021). "As FOXM1 is a phosphorylation target of ATR, we also investigated pFOXM1 in treated tumours." (PMID 34819497, 2021). "We found a switch from ERα-dependent to HER2-dependent and ERα-independent expression of FOXM1, which may enable disseminated ER+/HER2− cells to re-initiate tumor cell growth and metastasis formation in the presence of endocrine treatment." (PMID 33920089, 2021). "FAM188B knockdown reduced the levels of tumor proteins such as EGFR and FOXM1, suggesting that FAM188B may be a potential target controlling tumor malignancies." (PMID 33440835, 2021). "Our study demonstrates a novel positive regulatory between FoxM1 and AKR1C1 contributing cell growth and tumor progression of CCA and avasimibe may be an alternative therapeutic option for CCA by targeting this FoxM1/AKR1C1 signaling pathway." (PMID 34127944, 2021). "For example, FOXM1 gene expression in primary EOC, including HGSC, is highly overexpressed compared to normal epithelial ovarian tissues and directly correlates with the tumor stages and grade." (PMID 34205406, 2021). "Yet, the negative nearest neighbors of FOXM1 included genes functionally related to metabolic process, as a well appreciated mark of tumor transformation." (PMID 33479222, 2021). "In our current study, FOXM1 was not differentially expressed in tumor tissue from A-I KO vs A-I Tg hosts." (PMID 32477466, 2020).
tumor (continued). "The rate of FOXM1+ expression in ESCC was related to LNM, serosal invasion, and PTNM stage, but not with patient gender, age, anatomical location, gross morphology, degree of differentiation, or tumor diameter." (PMID 32035486, 2020). "Tumor growth was inhibited by treatment with tamoxifen plus GDC-0032, but not by tamoxifen alone, and this combined treatment resulted in decreased FOXM1 and LDHA expression." (PMID 32976773, 2020). "Additionally, molecular analysis showed that an NNT-AS1/miR-22/FOXM1 regulatory network in LUSC and NNT-AS1 silence exerted anti-tumor effects through the miR-22/FOXM1 axis in LUSC, providing a novel insight into the pathogenesis of LUSC." (PMID 32514270, 2020). "ALKBH5 demethylates Forkhead box M1 (FOXM1), which is one of the main tumor inducers." (PMID 33511112, 2020). "According to the Rab1A and FOXM1 IHC score of human CRC and adjacent normal tissues, it was illustrated as a cluster analysis diagram to demonstrate the differences in expression of the two proteins in tumor and normal tissues." (PMID 33214609, 2020). "Considering that FOXM1 is upregulated in many tumor types, and FOXM1 participates in RCC progression, OTUB1/FOXM1 axis may have broad role in tumor progression across multiple tumor types, especially in RCC." (PMID 32257108, 2020). "Therefore, we investigated the potential role of SATB2 in regulating GSC properties and GBM tumor growth, and found that SATB2 augmented GSC proliferation by recruiting histone acetyltransferase CBP to promote FOXM1 expression in GSCs." (PMID 33124191, 2020). "As FOXM1 is an oncogenic regulator that promotes GSC proliferation and expression of the stem cell marker SOX2, and SATB2 regulates FOXM1 expression, we next explored whether FOXM1 mediates the effects of SATB2 on GSC proliferation and tumor growth." (PMID 33124191, 2020). "Of the top 12 transcriptional regulators, CENPA, FOXM1, and MYBL2 were among the most highly expressed and displayed the largest differences in expression between tumor and normal tissues; each was >8 times more highly expressed in LUAD as compared to normal lung." (PMID 32925947, 2020). "FOXM1 directly binds to the human Cox-2 promoter and induces its expression in tumor and nontumor cells in inflammatory regions of injured lungs." (PMID 30992007, 2019). "To analyze knockout FOXM1 in regulation of proliferation inhibition and gemcitabine induced cell growth inhibition in vivo, we inoculated SW1990-WT/FK cells into nude mice and determined the tumor size at indicated time point post-inoculation." (PMID 30782607, 2019). "FOXM1 was found to be highly expressed in the nuclei of these ALK-expressing tumor cells with the surrounding benign cells being negative." (PMID 31390744, 2019). "FOXM1 promotes EMT and fosters tumor cell migration and invasion." (PMID 30710146, 2019). "In this work, we identified the pro‐tumorigenic function of FOXM1 by inhibiting maturation and antitumor response of bone marrow‐derived dendritic cells (BMDCs) in tumor‐bearing mice (TBM) and mimicking the tumor microenvironment (TME) through FOXM1‐Wnt family number 5A (Wnt5a) signaling." (PMID 30628173, 2019). "In conclusion, this study provides evidences that FOXM1 transcriptionally regulates UBE2C expression in ESCC and their deregulation may be a general phenomenon in human neoplasias." (PMID 29596365, 2018).
tumor (continued). "Moreover, numerous genes modified by m6A have been revealed to play regulatory roles in tumour formation, such as BCL2, PTEN, SOCS2, FOXM1 and HBXIP." (PMID 30031372, 2018). "Recently, researchers have found that FoxM1 expression is increased in human HCC and is closely related to the clinicopathological features of HCC; overexpression of FoxM1 in HCC tumor tissues is an independent prognostic factor for poor OS and DFS in HCC patients." (PMID 30580327, 2018). "We also evaluated the correlation between FOXM1 expression and the TNM stage of tumor." (PMID 28427178, 2017). "Finally, using orthotopic xenografts we demonstrated that inhibition of either FOXM1 or AGR2 in human PIMAs inhibited mucinous characteristics, and reduced tumor growth and invasion." (PMID 29267283, 2017). "FOXM1 and ABCC5 proteins in the tumor tissues were stained by immunohistochemistry." (PMID 28277541, 2017). "In addition, in the tumor tissues of combination group, the expression of MPM2 was also increased, whereas FOXM1 and BICD2 were reduced, and the quantity of Tunel-positive cells was dramatically induced by combination treatment." (PMID 28542137, 2017). "A difference in tumor growth was observed between FOXM1 overexpressing and control CRC cells, whereas the difference was more significant upon 5-FU treatment, indicating that FOXM1 conferred 5-FU tolerance to CRC cells." (PMID 28051999, 2017). "Moreover, in vivo study revealed that DT-13 combined with NVB significantly suppressed tumor growth in nude mice xenograft model, meanwhile, the changes of FOXM1 and BICD2 in tumor tissues further demonstrated the molecular mechanisms in vitro." (PMID 28542137, 2017). "In addition, in vivo study revealed that DT-13 combined with NVB significantly suppressed tumor growth in nude mice xenograft model, and downregulated the expression of FOXM1 and BICD2 in tumor tissues, which was consistent with in vitro study." (PMID 28542137, 2017). "Our past miRNA studies of BC cells showed that clustered miRNAs (including miR-1/133a (targeting TAGLN2), miR-23b/27b/24-1 (targeting EGFR, MET, and FOXM1), and miR-195/497 (targeting BIRC5 and WNT7A)) act as tumor-suppressive miRNAs through their regulation of several oncogenic genes and pathways." (PMID 27072587, 2016). "The results suggest that FOXM1 is required for growth of proliferating tumor cells but not for normal astrocytes." (PMID 27764801, 2016). "In this study, we developed a new way capable of directly delivering exogenous recombinant FoxM1 tumor antigens by fusion with CTP into the cytosol of DCs, indicating that exogenous tumor antigens can be recognized as endogenous antigens when delivered into the cytosol of DCs by CTP." (PMID 27351282, 2016). "Finally, FoxM1 inhibition combined with irradiation in a patient GBM-derived orthotopic model significantly impeded tumor growth and prolonged the survival of tumor bearing mice." (PMID 26444992, 2015). "Moreover, FOXM1 also accelerated angiogenesis via upregulation of VEGF expression and thereby promoted tumor metastasis." (PMID 26451068, 2015). "The doses of Thiostrepton used have been previously shown to down-regulate expression of FoxM1 in other tumor cell lines without any off target effect or toxicity to normal peripheral blood mononuclear cells (PBMNC)." (PMID 26159723, 2015). "However, more studies are needed to further understand the precise mechanisms of the FoxM1 and PTTG1 involved in different cellular contexts and tumor types, and in response to different types of damage." (PMID 26264222, 2015). "We could further detect a tendency of FOXM1 and STAT3 to be higher expressed in the metastasis group of tumor tissue than in the primary tumor group." (PMID 25797272, 2015). "The strong correlation of FOXM1 and STAT3 expression could be confirmed in lysates obtained from frozen primary and metastasis tumor material of GEP-NEN patients." (PMID 25797272, 2015).
tumor (continued). "Consistent with in vitro data, FoxM1-expressing cells were highly enriched in Sox2 positive tumor cells compared to Sox2 negative/low tumor cells." (PMID 26444992, 2015). "The prognosis of those patients with a strong tumor expression of FoxM1 was significantly poorer than that of patients with a negative or weak tumor FoxM1 expression (P<0.0001)." (PMID 23536876, 2013). "Working from knowledge that the tumor suppressor p14/p19ARF binds and inhibits FOXM1 protein, the late Costa and his colleagues developed a cell penetrating peptide, ARFWT, that mimics ARF-dependent inactivation of FOXM1." (PMID 24130802, 2013). "In both tumor types, FoxM1-dependent chemotherapy resistance was partially mediated by enhanced expression of DNA repair genes, BRIP, and Rad51, respectively, although it is likely that other FoxM1 targets with repair roles are also involved." (PMID 23467617, 2013). "Immunohistochemical analysis also confirmed that tumor tissues exhibited abundant FoxM1 expression, in contrast to adjacent nontumor tissues which displayed absence or lower FoxM1 expression." (PMID 23006512, 2012). "We first examined FoxM1 mRNA expression in 39 paired clinical samples from ccRCC patients (tumor tissues and matched adjacent nontumor tissues) by real-time quantitative PCR." (PMID 23006512, 2012). "We found that the protein level of FoxM1 in tumor tissues was significantly higher than that in adjacent nontumor tissues (P < 0.001), consistent with the results of real-time quantitative PCR." (PMID 23006512, 2012). "FOXM1 is an attractive target since it is not expressed in quiescent cells, and is required for cell cycle progression and viability in many tumor cell types." (PMID 22761781, 2012). "FoxM1 is expressed in glioma and pancreatic cancer cells and promotes angiogenesis by regulating VEGF expression, FoxO1/3/4 act as tumor suppressors in prostate cancer and leukemia, and recent evidence suggests that FoxC2 is a key factor in tumor development and disease progression." (PMID 22174714, 2012). "Therefore, we suggest the upregulation of genes in our model work together in regulating cell cycle and tumor progression, with HJURP ensuring chromosome stability, CDK1 driving mitotic entry, and FOXM1 promoting proliferation and CHEK1 supporting cell survival under DNA damage conditions." (PMID 40299539, 2025). "However, cisplatin (/CDDP) did not substantially reduce FOXM1 levels in these xenograft tumor tissues." (PMID 40630538, 2025). "Notably, the TME-mediated induction of FOXM1 in OCSC is crucial for their survival in the omental niche, but also a vulnerability that, if successfully targeted, may improve the response of tumor cells to drug treatments." (PMID 38806454, 2024). "We speculated that the tumorigenesis of tumor cells with unaffected FOXM1 expression by asciminib may not be much altered by c-ABL inhibitor treatment too." (PMID 39060421, 2024). "However, the role of FOXM1 expression in EMPD tumorigenesis and tumor progression remains unclear, as little information is available on its expression in EMPD." (PMID 38374400, 2024). "In addition, IHC analysis of tumor tissues in four groups showed that silencing of NAT10 led to the downregulated ki67 expression, while the ki67 expression was enhanced again after overexpression of FOXM1." (PMID 37948132, 2023).
tumor (continued). "However, FOXM1 Apt cannot enter tumor cells alone because there is no specific ligand for this aptamer on the surface of the cell membrane and the aptamer is repelled through the negative charge of the cell membrane." (PMID 37736517, 2023). "However, FOXM1 did not affect tumor growth at early (day 40) or late (day 56) time points throughout tumor progression." (PMID 37452072, 2023). "Similarly, we also found that FOXM1 overexpression could stimulate HGSOC cell viability and regulate tumor cell cycle." (PMID 35624501, 2022). "Therefore, we evaluated the anti-tumor activity of CDI and investigated whether it suppressed the transcription of genes under FoxM1 control." (PMID 35884976, 2022). "Interestingly, when we compared the relative expression of FOXM1 and CENPF in HCC and NT, respectively, we observed that they were positively correlated with each other (r = 0.9258, p < 0.0001), and substantially higher expressions in the tumor samples." (PMID 35865168, 2022). "In addition, we found that the expressions of FOXM1, ADAM17, NOTCH1 and N-cadherin were decreased in SPAG5-downregulated tumor tissues, while E-cadherin expression was increased, highlighting the role of SPAG5 in downregulation of the expression of FOXM1, ADAM17 and NOTCH1, and inhibiting EMT." (PMID 35138218, 2022). "No studies have reported that FOXM1 could bind to the ENO1 promoter to stimulate the proliferation of tumor cells." (PMID 34504528, 2021). "The RT-qPCR, Western blot and IHC results indicated that overexpression of FOXM1 upregulated the expression of Linc-ROR, LMO4, and Ki-67, while silencing of Linc-ROR downregulated the expression of LMO4 and Ki-67 as well as unchanged FOXM1 expression in the tumor tissues." (PMID 34447693, 2021). "Importantly, silencing of FOXM1 and WEE1 also impaired subcutaneous tumor formation by STS cells." (PMID 33564073, 2021). "Moreover, the knockdown of FOXM1 has been reported to encumber the proliferation and invasion of HNSCC cells, along with a more differentiated-like phenotype in three-dimensional culture and Xenograft tumor models." (PMID 34447693, 2021). "Taken together with the results of our immunohistochemical studies, which shows that around 70% of DKK1/FOXM1 double positive ESCC tumors are negative for β-catenin in the same tumor lesions, these results suggest that FOXM1 mainly controls DKK1 expression in ESCC." (PMID 34117362, 2021). "Interestingly, although FOXM1 overexpression alone appears to be insufficient in driving tumorigenesis in vivo, the absence of FOXM1 prevented tumor development in the colon and liver." (PMID 34205406, 2021). "FOXM1 is a member of the forkhead/winged helix box class O (FOXO) superfamily, and this transcription factor plays multiple roles in biological functions, such as facilitating tumor metastasis, cell proliferation, differentiation, invasion, resistance to stress, and DNA damage." (PMID 33407516, 2021). "Forkhead box M1 (FOXM1) is a tumorigenic FOX transcription factor believed to have a general role in the development and progression of tumors since it regulates the expression of numerous genes with significant roles in cell proliferation, migration, apoptosis, and tumor angiogenesis." (PMID 34768915, 2021). "However, there were few studies on the expression and clinical value of FOXM1 in tissues or serum of tumor tissues, and the analysis of FOXM1 expression in serum exosomes of tumor patients has not been reported yet." (PMID 33971889, 2021).